CETP (cholesteryl ester transfer protein)
Diseases named in the same sentence as CETP in open-access papers (continued):
Sharing a sentence is not in itself a finding about the gene and the disease.
cancer (21 papers, 2009 to 2025). A tumor composed of atypical neoplastic, often pleomorphic cells that invade other tissues. "Contrary to some prior studies, we found little evidence to support associations of other lipid-perturbing targets (eg, PCSK9, CETP) with cancer risk (eg, breast, prostate, head and neck)." (PMID 40511612, 2025). "Our study found a causal association between increased CETP and EC risk, which is consistent with the effect of CETP on other cancers." (PMID 39193372, 2024). "Furthermore, analysis of cell line, tissue and patient data available in publicly available databases linked elevated CETP expression to cancer, cancer relapse and overall poor survival." (PMID 28050232, 2016). "We employed cis-Mendelian randomization and colocalization to evaluate the role of 5 lipid-perturbing drug targets (ANGPTL3, ANGPTL4, APOC3, CETP, and PCSK9) in risk of 5 cancers (breast, colorectal, head and neck, ovarian, and prostate)." (PMID 40511612, 2025). "Similar benefits have been reported for other types of cancers with the use of specific CETP inhibitors." (PMID 39057711, 2024). "Overall the enrichment of most inflammatory pathways and the hepatic fibrosis signalling pathway was larger in the E3L.CETP mice, while the enrichment in the cancer related pathway was lower." (PMID 33658534, 2021). "Inhibiting CETP was envisaged as a viable strategy to prevent coronary heart disease, and despite leading to several failed clinical trials its role in cancer has been overlooked." (PMID 28050232, 2016). "Studies have shown that CETP in cancer cells may affect the release of Cyt c and apoptosis sensitivity by changing mitochondrial cholesterol metabolism." (PMID 40860340, 2025). "Nonetheless, our findings suggesting little evidence of association of genetically proxied ANGPTL3, APOC3, CETP, and PCSK9 inhibition with cancer risk may help to deprioritize further evaluation of these proteins as intervention targets for cancer prevention." (PMID 40511612, 2025). "We employed drug-target Mendelian randomization (MR) to systematically evaluate the effect of 5 approved or emerging lipid-perturbing drug targets for CVD (APOC3, ANGPTL3, ANGPTL4, CETP, and PCSK9) on risk of 5 cancers (breast, colorectal, head and neck, ovarian, and prostate)." (PMID 40511612, 2025). "A pilot xenograft mice study corroborated CETP’s function as a cancer survival gene." (PMID 39193372, 2024). "Subsequently cholesteryl ester transfer protein (CETP) expression in cancer cells is also increased, which could be explained by the crucial role of CETP in stabilizing the CEs and promoting their storage in lipid droplets." (PMID 34869315, 2021). "Notably, CETP may play an essential role in cancer development and maintenance primarily by affecting the cholesterol balance inside and outside cancer cells." (PMID 39193372, 2024). "Emerging evidence from preclinical and clinical studies supports the beneficial effects of CETP inhibitors and recombinant HDL-C (rHDL) particles in treating inflammatory diseases, improving glucose metabolism, and potentially combating certain cancers." (PMID 39057711, 2024). "Among them, the upregulation from the early-stage cancer to more advanced stages were the strongest for RNASE2, SERPINE1, and CETP." (PMID 33828156, 2021). "In Lu and co-workers’ scRNA-Seq dataset (GSE149614), > 66% of macrophages in para-carcinoma tissue expressed CD5L, CETP, MARCO, and CFP, in contrast to < 22% of macrophages in HCC tissue." (PMID 34001107, 2021). "We employed two large-scale bulk HCC RNA-Seq/microarray datasets to compare the expression of HAMP, CD5L, CETP, MARCO, and CFP between HCC and para-carcinoma tissue samples." (PMID 34001107, 2021). "CETP, as a transfer protein that enables cholesteryl ester transfer between HDL and -triglyceride-rich lipoproteins, is a well-known contributor to cardiovascular diseases, but its function in cancer is still insufficiently investigated." (PMID 33805921, 2021).
cancer (continued). "While ITCs have been shown to exert pleiotropic effects against cancer, CETP was shown to affect cancer and healthy cells in a non-selective way by inducing cell death of HepG2 cells and primary mouse hepatocytes by necrosis." (PMID 28690627, 2017).
infection (21 papers, 2009 to 2025). The state of being infected such as from the introduction of a foreign agent such as serum, vaccine, antigenic substance or organism. "Changes in the expression of the LOX, ABCA1 and CD36 genes in the CETP mice indicate a possible association between lipid metabolism and the response to infection." (PMID 38966642, 2024). "One CETP inhibitor, torcetrapib significantly increased the risk of infection- and malignancy-associated mortality in patients with high cardiovascular risk." (PMID 30736368, 2019). "This genetic mutation is exclusively found in East Asia, overlapping with the current and historic regions of Schistosoma japonicum epidemic, so that this infection could be related to high prevalence of CETP deficiency in East Asia." (PMID 35372338, 2022). "CETP activity has been reported to be associated with poor prognosis of infection." (PMID 34124081, 2021). "In this study, we explored the role of BAT thermogenesis in infection-triggered fever in APOE∗3-Leiden.CETP mice, a well-recognized model for human-like lipoprotein metabolism." (PMID 39128824, 2024). "In this context, the presence of CETP demonstrated a more effective response based on infection control and tissue repair." (PMID 38966642, 2024). "In the present study, we investigated the impact of CETP expression on infection development and the inflammatory response in murine CL." (PMID 38966642, 2024). "Under in vitro conditions, although the approach is restricted to an isolated cellular system disregarding the organism’s response, a reduction in arginase activity was observed in the CETP group compared with the WT group at 4 hours after infection." (PMID 38966642, 2024). "The CD36 receptor was negatively regulated in the presence of infection in the CETP group, correlating with healing and a decrease in parasite load." (PMID 38966642, 2024). "Considering the dynamics of the lesion and healing, the CETP group showed faster resolution compared with the WT group after the 10th week of infection." (PMID 38966642, 2024). "Attention to the role of CETP in immune response has increased because of the large number of infection-related deaths in the ILLUMINATE trial in which the CETP inhibitor torcetrapib was studied." (PMID 35897703, 2022). "Inhibition of CETP can be an approach to block this process and prevent the liver complication when the infection outbreak is feared such as a case of major flooding in the endemic region." (PMID 35372338, 2022). "The data indicate that the presence of CETP plays an important role in resolving Leishmania (L.)amazonensis infection, reducing parasitism, and modulating the inflammatory response in controlling infection and tissue repair." (PMID 38966642, 2024). "Analyzing the percentage of infection, CETP cells showed 84% at 4 h and WT cells, 76%." (PMID 38966642, 2024). "However, the progression of the lesion over 12-weeks post- infection, showed an inversion in the response, where the CETP animals presented a lower density of amastigotes in the lesions compared with the WT group and the 4-week period." (PMID 38966642, 2024). "Furthermore, we identified a previously unrecognized effect of CETP inhibition in enhancing macrophage activation and infiltration, leading to resolution of infection." (PMID 38646937, 2024). "In the infection of S. japonicum in the mouse model, the number of the aberrant eggs in the liver was not different between the wild-type and CETP-transgenic mice, but the ectopic embryonation to miracidia was significantly more in the CETP-transgenic mice." (PMID 35372338, 2022). "This suggests that metabolically-induced and infection-related inflammation may have different effects on the expression and production of CETP by Kupffer cells." (PMID 31292457, 2019). "However, the CETP group, after 12 weeks, showed remodeling and healing observed in the deeper layer, while the WT group, still in the inflammatory process, showed delayed infection development." (PMID 38966642, 2024).
infection (continued). "This may be an off-target effect of torcetrapib because other large RCTs of CETP inhibitors dalcetrapib, evacetrapib, anacetrapib did not validate increased risk of severe infection." (PMID 30736368, 2019). "Infection and inflammation are associated with changes in the activity of plasma proteins that regulate the HDL composition, such as lecithin cholesterol acetyltransferase (LCAT), phospholipid transfer protein (PLTP), and cholesteryl ester transfer protein (CETP) mainly." (PMID 27293313, 2016). "During infection, the LP profile showed an increase in triglycerides in the VLDL fraction in the CETP group at 12 weeks." (PMID 38966642, 2024). "Similar to the results obtained from APOE∗3-Leiden.CETP mice, TG-derived FA uptake by BAT and WAT depots was increased upon infection of wild-type mice." (PMID 39128824, 2024). "Modulation of infection in the presence and absence of CETP was also assessed in the in vitro culture of murine macrophages infected with L. (L.)amazonensis promastigotes." (PMID 38966642, 2024). "After 12 weeks of infection, the CETP mice showed an increase in the concentration of TG in VLDL and a reduction in LDL and HDL, compared with the analysis carried out at week 4 post-infection." (PMID 38966642, 2024). "Lower expression of CETP mRNA was observed in the Leishmania infection in the 4th and 12th weeks compared with the control without infection." (PMID 38966642, 2024). "To determine if CETP inhibition regulates proinflammatory cytokine production at the transcriptional level, we examined the mRNA levels of IL-6, IL-1β, and TNF-α using quantitative PCR (qPCR) at 72 hours after infection." (PMID 38646937, 2024). "In this regard, surprisingly, a CETP inhibitor (Torcetrapib) in the ILLUMINATE trial increased the frequency of infection cases, although this did not occur with other inhibitors." (PMID 34367144, 2021). "Indeed, based on the protective effects of HDL-C/ApoA-I replacement strategies and cholesteryl ester transfer protein (CEPT) inhibition in septic shock, there is increasing recognition of the role of HDL-C in infection control, including the direct antiviral effects of HDL-C." (PMID 33793566, 2021). "However, trials in humans using CETP inhibitors failed to protect against cardiovascular diseases and one of them (torcetrapib) increased the incidence of cancer and infection." (PMID 27293313, 2016). "The effects of intravenous (iv) infusion of purified LPS or polymicrobial infection (cecal ligation and puncture [CLP]) were compared in transgenic mice expressing human CETP and wild-type mice naturally having no CETP activity." (PMID 33500240, 2021).
metabolic disease (15 papers, 2016 to 2025). A congenital disorder (due to inherited enzyme abnormality) or acquired (due to failure of a metabolically important organ) disorder resulting from an abnormal metabolic process. "Future clinical trials can explore whether CETP inhibitors can be repurposed to treat metabolic disease and provide an oral therapeutic option to benefit high-risk patients before escalation to injectable drugs such as insulin or glucagon-like peptide 1 (GLP1) receptor agonists." (PMID 37398493, 2023). "This positions CETP inhibitors as potential candidates for repurposing in metabolic disease treatment." (PMID 38962682, 2024). "Here, we aimed to unveil the mechanisms underlying the protective effects of FGF21 on NASH using APOE*3-Leiden.CETP mice, a well-established model for human-like metabolic diseases." (PMID 36648330, 2023). "Future clinical trials should explore the protective effects of combining SGLT2 inhibitors and CETP-lowering treatments in the context of metabolic disease prevention." (PMID 37398493, 2023). "We next performed another long-term experiment in hyperlipidemic female APOE∗3.Leiden-CETP mice, which are mice with a humanized lipid metabolism that are prone to developing metabolic disease." (PMID 33548499, 2021). "We explored the relationship between circulating PCSK9 levels and CETP activity in patients with metabolic disease who were not on lipid-lowering therapy." (PMID 27488210, 2016).
tumor (10 papers, 2009 to 2025). "Analysis of differentially expressed genes using Ingenuity Pathway Analysis (IPA), in vivo tumor inhibition, and in vitro phenotypic responses to AP revealed a unique CETP-centric cholesterol pathway involved in sensitizing ER+ BC cells to intrinsic mitochondrial apoptosis." (PMID 28050232, 2016). "Proteins in HLH cluster, implying the recovery of tumor-inhibited protein expression after the DBT, participated in lipid binding and antioxidant activity (APOM, CETP, and ALB)." (PMID 38719824, 2024). "Compared to normal tissues, significantly higher expression for SKAP1, LAT and lower expression for CD1D, CD79B, CETP, PTGDS was found in tumor tissues in the TCGA-BRCA cohort." (PMID 37598257, 2023). "Based on the expression levels of four proteins: CETP, HGFL, L1CAM, and LAIR2, combined with tumor diameter, serum AFP, and GGT concentrations to establish a preoperative MVI status prediction model for HCC patients." (PMID 38049860, 2023). "Of the three CETP inhibitors only JTT-705 is predicted to bind to these receptors and hence have the ability to control cell proliferation and tumor progression." (PMID 19436720, 2009). "The direct interaction between Cyt c and CETP, CLEC11A, CYP2A6 and CYP2A7 has not been clearly revealed, but they have potential indirect associations in cholesterol metabolism, mitochondrial function, oxidative stress regulation and tumor microenvironment regulation." (PMID 40860340, 2025).
heart disease (3 papers, 2018 to 2023). "This protein controls the exchange of cholesteryl esters and triglycerides between HDL and low-density lipoproteins (LDL), and higher CETP would be expected to result in a less favorable LDL/HDL ratio, which is associated with heart disease." (PMID 37179299, 2023). "Although these animal models can exhibit some of the components of different complex pathologies, mice and rats for example are deficient in cholesteryl ester transfer protein (CETP) and thus resistant to the development of heart disease, due to important differences in lipid metabolism with humans." (PMID 29850391, 2018).
infectious disease (3 papers, 2016 to 2022). A disorder directly resulting from the presence and activity of a microbial, viral, or parasitic agent in humans. "Data from the ILLUMINATE trial showed that raising HDL-C with torcetrapib, a cholesteryl ester transfer protein (CETP) inhibitor, resulted in an increased risk of infectious disease-related deaths compared to placebo." (PMID 33947039, 2021).
genetic diseases (2 papers, 2021 to 2022). "The study population is otherwise a past geographical isolate with founder effects of various genetic diseases like cholesteryl ester transfer protein (CETP) deficiency." (PMID 33919892, 2021).
electrolyte imbalance (1 paper, 2017). "Although Torcetrapib showed a higher efficiency of CETP inhibition, large clinical trials have been halted because of side effects on blood pressure and/or electrolyte imbalance." (PMID 28911944, 2017).
liver (1 paper, 2024). "CETP activity has been shown to be mainly determined by plasma TAG levels, rather than by IR, which indicates that potentially increased CETP action in individuals with liver IR may be primarily attributable to the increased postprandial TAG in the circulation, and not to the hepatic IR itself." (PMID 38493102, 2024).
neurodegenerative disease (1 paper, 2012). A disorder of the central nervous system characterized by gradual and progressive loss of neural tissue and neurologic function. "In the past decade, while a number of case–control studies have been carried out to investigate the relationships between LIPC or CETP polymorphisms and risk of atherosclerosis diseases, little is known about their effect on neurodegenerative disease." (PMID 23181436, 2012).
CETP also shares sentences with these, for which no sentence is quoted: arteriosclerosis (2 papers); chronic kidney disease (2); familial dysbetalipoproteinemia (2); gastric cancer (2); Glucose intolerance (2); inflammation (2); injury (2); mixed hyperlipidemia (2); Parkinson disease (2); acute myocardial infarction (1); alcoholic steatohepatitis (1); aortic aneurysm (1); atrial fibrillation (1); Atrophy (1); bacterial infections (1); bladder cancer (1); Cerebral ischemia (1); cerebral small vessel disease (1); diabetic kidney disease (1); diabetic neuropathy (1); End Stage Liver Disease (1); fetal growth restriction (1); genitourinary cancer (1); gout (1); gram-negative bacterial infections (1); hemorrhagic stroke (1); Hypoglycemia (1); Impaired glucose tolerance (1); left ventricular hypertrophy (1); leukemia (1).
A further 24 diseases each share a sentence with CETP in 1 paper.